IL10 (interleukin 10)
Diseases named in the same sentence as IL10 in open-access papers (continued):
Sharing a sentence is not in itself a finding about the gene and the disease.
tumor (continued). "Another mechanism for the antitumor action of IL-10 is the increased CD8 + T cell infiltration and IFN-γ level in tumor tissues induced by IL-10." (PMID 38520006, 2024). "Equilibrium in immunoediting illustrates humoral levels of low anti-tumor (Interleukin-12 (IL-12), IFN-γ) cytokines compared with high tumor-promoting cytokines (TGF-β, IL-10, IL-23)." (PMID 38994941, 2024). "GAMs produce anti-inflammatory cytokines (such as IL-4, IL-10, and TGF-β), tumor-promoting factors (including IGF-1, EGF, and PDGF), angiogenesis mediators (like VEGF and IL-8), and metabolic disruptors (e.g., ARG1 and IDO)." (PMID 38732975, 2024). "The presence of cytokines such as IL-10 and TGF-ß, secreted by MDSCs, TAMs and other immune cells, as well as tumor cells, further suppress NK cells." (PMID 39759523, 2024). "The major cellular sources of IL-10 are CD4+ T cells, CD8+ T cells, a subset of Tregs and tumor cells." (PMID 39235457, 2024). "Tumor-derived versican dampens DC function by binding to TLR2 and forming a positive feedback loop characterized by the upregulation of IL-10/IL-6 receptors, resulting in tumor immunosuppression." (PMID 38946426, 2024). "These cells then produce anti-inflammatory cytokines such as IL-10 and TGF-β, suppressing the body's natural anti-tumor immune response." (PMID 38249783, 2024). "This pattern is completely logical as inhibition of IL-10 allows for less immunosuppression, more angiogenesis, and more VEGF, IL-1β, TNF-α, IL-6, MMP-9, and NF-κB activation, which encourages tumor volume." (PMID 39451257, 2024). "The M2 macrophages secrete anti-inflammatory molecules, including resistin-like-α, IL-10, Arginase-1, and mannose receptor C type 1 (MRC1), which help in resolution of inflammation and remodeling of injured lung tissue and tumor progression." (PMID 39120378, 2024). "Analyses of the cellular make up of tumor-infiltrating leukocytes detected a reduced percentage of FoxP3+ (p = 0.001) CD4+CD25+ cells and IL-10+ (p = 0.0001) CD4+CD25+FoxP3+ cells in metformin-treated mice compared to the non-treated group." (PMID 38892058, 2024). "Tumor cells exhibit the capacity to secrete factors such as transforming growth factor-beta (TGF-β) and interleukin-10 (IL-10), fostering an environment of immunosuppression." (PMID 38217016, 2024). "On the contrary, cytokines such as IL-10 and TGF-β derived from tumor cells and Treg cells inhibit the anti-tumor immune effect." (PMID 38887597, 2024). "Recent studies have highlighted the significant roles of cytokines such as IL-10, IL-17, and TNF-α in immune regulation and tumor progression." (PMID 39456637, 2024). "Cytokines such as CCL17 and CCL15 expressed from TAMs attract regulatory T cells (T regs) into the tumor stroma, whereas IL-10 and TGF-β suppress T-cell-mediated anti-tumor immune responses." (PMID 38672714, 2024). "EP2/4-mediated effects on MDSCs are IL-10 production, COX-2 upregulation, or the ability to suppress anti-tumor NK and T cell responses." (PMID 38343540, 2024). "IL-6-mediated STAT3 activity in tumor cells can stimulate the release of factors, such as VEGF and IL-10, that inhibit DC maturation." (PMID 38254801, 2024). "The M2 cells' secretion of cytokines such as IL10, EGF, and VEGF can inhibit T cell proliferation and promote tumor growth and angiogenesis." (PMID 38110895, 2023). "During tumor progression, Th2 cells are recruited to the TME by CCR3 ligands (CCL26, CCL11, and so on), and produce IL-4 and IL-10, which induce M2 polarization of macrophages." (PMID 37063892, 2023). "Tregs, by secreting IL-10 and TGF-β1, inhibit osteoclast differentiation and bone resorption, potentially exerting specific effects on tumor cells, culminating in a more positive prognosis." (PMID 37980450, 2023). "Chronic inflammatory cytokines such as IL-6, IL-10 and TGF-β were found to be important in mediating the expansion and suppressive functions of MDSCs, resulting in tumor angiogenesis, development and metastasis." (PMID 37108179, 2023).
tumor (continued). "For instance, it has been found that extracellular vesicles derived from tumor cells carry immunosuppressive molecules such as transforming growth factor-beta (TGF-β), interleukin-10 (IL-10), and indoleamine 2,3-dioxygenase (IDO)." (PMID 37670933, 2023). "Among the cytokines or cytokine/receptor pathways used in clinical trials for the treatment of metastatic melanoma we must mention IL-2, IL-8, IL-10, IL-12, IFN-α and TNF-α, as well as tumor growth factors." (PMID 36768978, 2023). "Tumour-derived cytokines, including IL-6, IL-10, and transforming growth factor (TGF)-β1, also hinder tumour antigen processing and presentation by DCs." (PMID 37454231, 2023). "Produce immunosuppressive cytokines, such as IL-10, IL-35, and TGF-β; induce effector T and B cell malfunction; promote the proliferation of Treg cells and MDSCs; promote tumor progression and metastasis." (PMID 37868967, 2023). "Pro-tumorigenic chemo/cytokines such as IL-6, IL-10, CCL2, and CCL5 were decreased in NLRC5+ tumor-bearing ascites, correlating with significantly decreased frequency of tolerogenic DC2s subsets in this compartment." (PMID 38235131, 2023). "It inhibits the generation of M2 markers, IL-10, MMP-2/9, VEGF, and MCP-1, which is major determinants of macrophage recruitment at tumor sites." (PMID 37560476, 2023). "PGE2-PTGER3 signaling has been shown to mediate the polarization of TAMs towards a pro-tumor phenotype, and promote the production of immunosuppressive factors (TGF-β (transforming growth factor-beta) and IL-10 (interleukin-10))." (PMID 37999824, 2023). "During the burn-induced inflammatory response, pro-inflammatory cytokines such as IL-6, IL-8, tumor TNF-α, and anti-inflammatory cytokines such as IL-10 are released." (PMID 37090725, 2023). "Bregs, a novel B cell subset, secrete IL-10 and TGF-β to dampen immune responses and boost tumor growth." (PMID 37892995, 2023). "MDSCs suppress the body’s adaptive immune response to tumor cells, inhibiting T cells and NKCs within the TIM by expressing arginase, inducible NOS, TGF-β, IL-10, and COX2, as well as by increasing the local Treg population, among others." (PMID 37766141, 2023). "High amounts of IL-10, TGF-, and VEGF expression by M2d macrophages make them a significant inflammatory component of tumor tissues, encouraging angiogenesis and cancer spread." (PMID 37138860, 2023). "For example, in HNSCC, tumor cells decrease the production of IFN-α by pDCs through the binding of CD317 and ILT-7, as well as the production of TGF-β, PGE2, and IL-10." (PMID 37817484, 2023). "Wherein, in BLCA tumor, CSF1R (rho = 0.706), HAVCR2 (rho = 0.686), IL-10 (rho = 0.682), and PDCD1LG2 (rho = 0.753) showed the strongest positive correlation with FAP expression." (PMID 37166418, 2023). "Immunosuppressive cytokines, such as IL-6 and IL-10, interfere with the antitumor effects of CD8+ and CD4+ T cells in the tumor microenvironment." (PMID 36639681, 2023). "Although a paradoxical role of IL-10 has been revealed in human cancer studies, the functions of IL-10 and the relationship between IL-10 and IFN-γ in MDV tumor formation remain to be elucidated." (PMID 36851499, 2023). "pDC expression of tolerogenic factors such as IL-10, TGF-β, and IDO supports pDC pro-tumor immunity." (PMID 37766141, 2023). "For example, studies have suggested that tumor-promoting Th2 cells have high levels of IL-10 and TGF-β, whereas Th2 cells with high expression of IL-3, IL-5, IL-13, and GM-CSF exhibit pro-inflammatory and anti-tumor immunity." (PMID 37332039, 2023). "When it comes to cancer, M2-like macrophages support angiogenesis by secreting adrenomedullin and VEGFs and express immunosuppressive molecules such as IL-10, programmed cell death ligand 1 (PD-L1), and TGF-β, favoring tumor growth." (PMID 37533070, 2023). "IL-10 is a central mediator of immunosuppression in the TME, which promotes tumor progression and therapy resistance not only in EOC but also in other cancers." (PMID 37376134, 2023).
tumor (continued). "ELISA analysis of macrophage culture supernatants provided convergent data, showing that GBM tumor cells treated with shCCL21 siRNA to knockdown Ccl21 produced less VEGF-A and IL-10 than shCTRL-transduced GBM cells." (PMID 37314567, 2023). "This unique subpopulation of T cells secreting interleukin-10 (IL-10) and transforming growth factor (TGF)-β1 mediates immune system suppression in the tumor microenvironment and hence favours pro-tumour immunity." (PMID 37568595, 2023). "At the tumor site, immunosuppressive cells produce immunosuppressive cytokines, such as TGFB, IL-10 and IL-6, playing a key role in reducing the antitumor function of T cells." (PMID 36979400, 2023). "TLR signaling also induces the production of immunosuppressive cytokines (e.g., IL-10, TGF-β, and indoleamine 2,3-dioxygenase (IDO)) and thus further suppress the anti-tumor immune response." (PMID 38038814, 2023). "IL-10 and IL-23 secreted by macrophages reinforce this differentiation, promoting IL-10 and TGF-β expression, thereby suppressing tumor cell killing." (PMID 36831498, 2023). "We found that a significant gradient toward the serum (CXCL9, IL6, IL10, IL13) or the tumor tissue (IL1B) exists for all cytokines in question." (PMID 36980700, 2023). "IL-10 and TGF-β play a crucial role in creating an environment that suppresses the immune system, thereby facilitating tumor growth and spread." (PMID 38136358, 2023). "TECs also induce immune suppressive CD4+ T cells that influence CD8+ T cells through interleukin 10 (IL-10) and transforming growth factor-β (TGF-β) levels, which contribute to tumor immune evasion." (PMID 37666809, 2023). "These macrophages are involved in mechanisms of immunosuppression through the stimulation of Tregs and the secretion of cytokines such as TGF-β and IL-10, establishing a TME favorable for tumor progression." (PMID 37631922, 2023). "TAMs and other tumor-promoting cells in TME can also facilitate the polarization of monocytes toward TAMs by releasing IL-4, IL-10, IL-13, and TGF-β." (PMID 37221555, 2023). "Specific factors produced by activated T cells, tumor, and tumor stromal cells, such as VEGF, CSF, IL-6, IL-10, MMP-9, TGF-β, NF-kB, and other immune-suppressive mediators, can stimulate the proliferation and activation of MDSCs." (PMID 37857728, 2023). "IL-10 and TGF-β secreted by M2 macrophages can inhibit the activation of CTL and NK cells, reduce their killing effect on tumor cells, and indirectly promote tumor proliferation." (PMID 36937841, 2023). "Tumor cells can produce inhibitors that suppress the immune response, such as prostaglandin E2, TGF-β, and interleukin-10, as well as LAG-3, thereby leading to immune evasion." (PMID 38077373, 2023). "Further, AML blasts also secrete various immunosuppressive cytokine and chemokines such as IL-10, TGF B, IL-35 into the tumor microenvironment giving it an immune-inhibiting property." (PMID 37228595, 2023). "For example, tumor cell-secreting cytokines such as TGF-β and IL-10 have been shown to suppress DC function." (PMID 37766141, 2023). "In tumor ovaries, CISH was examined in early and late stages (n = 14 each, all subtypes) while IL-10 and GRP78 expression were examined in early and late stage HGSC (n = 5 each)." (PMID 36830840, 2023). "The presence of immunosuppressive cytokines (e.g., IL-10, TGF-, and IDO) in the TME prevents tumor cell clearance by NK cells." (PMID 36900322, 2023). "Immature myeloid cells become immunosuppressive MDSC under the combined influence of tumor-derived IL-1β, IL-6, and S100A8-9, as well as IFN-β, IL-4, IL-13, and IL-10 released by activated T cells." (PMID 37415162, 2023). "This enhanced 15-LOX2/15(S)-HETE activity in the RCC tumor microenvironment positively affects the production of the proinflammatory chemokine CCL2 and immunosuppressive cytokine IL-10, thus promoting local immunosuppression and tumor evasion." (PMID 36834678, 2023).
tumor (continued). "IL-10, a tolerance-inducing molecule in the HCC TME, is produced by tumor cells, TAMs, Treg cells, and DCs." (PMID 36845131, 2023). "Blocking cytokines secreted by CAFs (such as IL-6, IL-8, IL-10 and TGF-β) combined with PD-1/PD-L1 can improve the anti-tumor immune response through increasing T cell infiltration and alleviating the role of PD-1 in inhibiting T cell activity." (PMID 37064113, 2023). "Under the influence of GBM, GAMs are a major source of inflammatory cytokines (e.g., IL-1β, IL-8, IL-10) and chemokines (e.g., CCL2, CCL4, CCL5) that support GBM growth and mitigate anti-tumor immune function." (PMID 37368789, 2023). "In HCC, besides IL-10 released by TAMs impairs the cytotoxicity of downstream CD8+ T cells and NK cells, increases the frequency of FOXP3+Tregs within tumours, and inhibits the activation of CD4+ CD25− T cells." (PMID 37426674, 2023). "The presence of anti-inflammatory cytokines such as IL-4, IL-10, colony-stimulating factor (CSF), and TGF-β promotes the differentiation of recruited Mø into TAMs, which, in turn, enhance tumor cell growth." (PMID 38258072, 2023). "While myeloid derived suppressor cells are likely the major source of IL10 in CRC37, we found that HES1 downregulation in CRC cells increased IL10 expression suggesting a potential tumor-intrinsic role of IL10 in the pathogenesis of HES1 (−) CRCs." (PMID 37749297, 2023). "It promotes M2 polarization of TAMs by regulating IL-10 secretion mediated by the c-myc/PKM2 pathway, thereby promoting tumor growth, invasion, and metastasis." (PMID 37234990, 2023). "The M2c population—stimulated by IL10, TGF-β, and glucocorticoids—promotes tumor growth and is involved in immunoregulation, matrix deposition and tissue remodeling." (PMID 37759870, 2023). "High concentrations of cytokines, particularly IL-10, can induce HHLA2 expression in monocytes but fail to upregulate HHLA2 expression in clear cell kidney cancer cells; however, the tumor microenvironment in NSG mice can induce HHLA2 expression." (PMID 37891555, 2023). "While these data would be consistent with IL-23R pathway activation in tumor tissue, STAT3 activation can also be mediated by IL-6 or IL-10." (PMID 38375204, 2023). "Interleukins, such as IL-2, IL-10, IL-12, IL15, and IL-21, and their receptors have been shown to be efficient mediators of anti-tumor immunity in preclinical cancer models." (PMID 37240247, 2023). "Generally, tumor‐infiltrating Mφ tends to be polarized to M2 Mφ that presents as a pro‐tumoral phenotype and releases VEGF, TGF‐β, and IL‐10, which promote angiogenesis and immunosuppression, as well as facilitate tumor progression." (PMID 37009412, 2023). "The IgA-producing plasma cells can also co-express IL-10 and PD-L1, which suppress CTL responses, induce effector T cell exhaustion, and accelerate tumor development." (PMID 37868967, 2023). "Tumor-evoked CD19+CD81+CD27+pSTAT3+ regulatory B cells producing IL-10 and TGF-β suppressed T cell responses in the spleen and supported tumor growth in experimental fibrosarcoma." (PMID 38136307, 2023). "IL-23 promotes M2 macrophages and neutrophils infiltration and releases immunosuppressive cytokines, such as TGF-β, IL-10 and VEGF, which reduce CD8+ T cells proliferation and suppress anti-tumor responses." (PMID 36845095, 2023). "The upregulation of both IL-10 and IFN-γ has been reported in human cancer, and it has been proven that IL-10 enhances IFN-γ and granzyme production in tumor-infiltrating CD8+ T cells." (PMID 36851499, 2023). "For example, tumor releases IL-8, IL-10, PGE-2, and TGF-β to interstitially induce tumor progression N2 TANs and promote tumor growth and metastasis." (PMID 37063873, 2023). "IL-10 and RANTES are known to be secreted by cancer and stromal cells but also by immune cells; therefore, experimental data on their role on tumor growth remain controversial." (PMID 37759302, 2023).
tumor (continued). "M2 macrophages can secrete suppressive cytokines such as TGF-β and IL-10, producing an immunosuppressive TME that promotes tumor progression." (PMID 37711849, 2023). "Subsequently, Th cells, in turn, remodel tumor TME partly by altering the polarization direction of macrophage, as Th2 cells secrete IL-4, IL-5, and IL-10 to induce more M2 macrophages." (PMID 38274812, 2023). "On the other hand, IL-1β, IL-6, IL-8, IL-10, IL-12, MCP-1, MIP-1β increased high grade tumor compared to low grade tumor." (PMID 37520880, 2023). "B lymphocytes can produce immunostimulatory cytokines (e.g., IL-6, IL-4, IL12p40, IL7, INF-γ, TNF, CCL3, IL-2, and colony-stimulating factor 2 CFS2 or GM-CSF) and anti-inflammatory cytokines (IL-10, TGF-β, IL-35) even within the tumor tissue." (PMID 37046842, 2023). "Tumor cells secrete cytokines such as VEGF, IL-10, PGE2 and TGF-β to inhibit the function of DCs, characterized by inhibited DC maturation, low MHC II and co-stimulatory molecule expression." (PMID 37936694, 2023). "In the early stages of tumor development, TAMs usually exhibit an M1 phenotype with high expression of iNOS and interleukin (IL)-12, and low expression of CD206, Arg-1 and IL-10." (PMID 37127625, 2023). "Using phosphoflow cytometry, reduced IL-4, IL-10, and IL-21-induced p-STAT6 and p-STAT3 were identified in tumor infiltrating lymphocytes (TILs) in follicular lymphoma tumors." (PMID 37741983, 2023). "M2 macrophages secrete anti-inflammatory cytokines, such as IL-6, IL-10, IL-13, TGF-β, and chemokines and proteases, such as Arginase1, MMP, and VEGF-A, which promote tumor growth, angiogenesis, and metastasis." (PMID 35895109, 2023). "Previous studies have shown that multiple cytokines, including IL-6 and IL-10, activate their receptors on GBM cells to promote tumor progression, whereas IL-7 reduces tumorigenicity and enhances the immune responses of CD8+ T cells." (PMID 37734869, 2023). "Tumor cells are known to release various cytokines (such as TGF-β, IL-10), mediators (including kynurenine, PGE2, etc.), and to recruit immunosuppressive cells (such as TAMs and MDSCs) that contribute to immune evasion." (PMID 37444608, 2023). "The immunosuppressive microenvironment, comprising CXL12, TGFβ, IL-10, VEGF, and IDO1, secreted by tumor cells (particularly in malignant ascites), Tregs and other immunosuppressive cells, drives the proliferation of immature and pDCS." (PMID 38164130, 2023). "Polarization to M2-type happens after secretion of TGF-beta, IL-4, IL-10 and IL-13 by TH2 and tumour cells." (PMID 37509293, 2023). "cGAS-STING participates in the remodeling of the tumor microenvironment (TME), which induces the production of antitumor cytokines such as interleukin 10 and invariant surface glycoprotein (ISG) that inhibit tumor growth." (PMID 36936940, 2023). "Tumor-infiltrating lymphocytes are often inactivated or exhausted due to immunosuppressive factors, including cytokines (IL-6, IL-10, TGF-β, galectin-1) secreted by tumor, stromal, and myeloid immune cells." (PMID 38087370, 2023). "First, tumor cells can secrete immunosuppressive cytokines or metabolic factors, such as transforming growth factor-β (TGF-β), interleukin-6 (IL-6), IL-10 and prostaglandin (PGE2), in an autocrine or paracrine manner to inhibit the killing of tumor cells." (PMID 37138865, 2023). "M2b macrophage-secreted IL10 promotes Treg cell differentiation from naive T cells, whereas secreted IL6 activates Th2 cells, which promote tumor progression." (PMID 38035101, 2023). "Activation of these pathways leads to increased levels of anti-inflammatory cytokines such as IL-10, TGF-β, and STAT3 contributing to the immunosuppressive environment and maintenance of the cold tumour environment." (PMID 37165457, 2023). "With the treatment of an equivalent molar ratio of BF10 or its subcomponents, IL-10-Fc and BF10 both significantly suppressed tumor growth, and BF treatment performed best among all groups." (PMID 37586318, 2023).